TSLP (thymic stromal lymphopoietin)
Diseases named in the same sentence as TSLP in open-access papers (continued):
Sharing a sentence is not in itself a finding about the gene and the disease.
autoimmune disease (19 papers, 2009 to 2025). A disorder resulting from loss of function or tissue destruction of an organ or multiple organs, arising from humoral or cellular immune responses of the individual to their own tissue constituents. "Epithelium-derived cytokines, such as IL-33, IL-25, and thymic stromal lymphopoietin are alarmins that are involved with type-2, type-1, and type-17 immune responses, and are associated with autoimmune diseases and allergic disorders." (PMID 39214920, 2024). "Several other molecules are shown to be induced by VIP in allergic and autoimmune diseases, including TSLP, TGF-β, and VCAM-1, all of which are implicated in the pathogenesis of EoE." (PMID 38391908, 2024). "More recently, TSLP is implicated in autoimmune diseases including psoriasis vulgaris and rheumatoid arthritis." (PMID 39726595, 2024). "These responses culminate in the production of a plethora of cytokines such as TSLP, IL-9, IL-25, and IL-33, which have been implicated in the pathogenesis of several inflammatory and autoimmune diseases." (PMID 37063828, 2023). "Depending on the immune cells targeted by TSLP, it is reported not only to promote Th2 response but also to be associated with autoimmune disorders and cancer." (PMID 30057581, 2018). "However, aberrant TSLP activity is implicated in various allergic, chronic inflammation and autoimmune diseases and cancers." (PMID 39726595, 2024). "Moreover, TSLP has been implicated in chronic inflammation, autoimmune diseases, and cancer." (PMID 36726974, 2022). "Studies suggest that, like TSLP, IL-25 plays a dual role in regulating the immune response during the development of autoimmune diseases." (PMID 40981017, 2025). "Here, we first discuss the major pathophysiological roles of TSLP and IL-7 in autoimmune diseases, inflammation and cancer." (PMID 32849527, 2020). "These original findings extend the role of TSLP from allergic disorders to IL-23-driven autoimmunity, with possible implication in other forms of autoimmune disorders (e.g., RA)." (PMID 30057581, 2018). "Second, TSLP was shown to contribute to the development of psoriasis, a widespread autoimmune disease, by regulating IL-23 production by DCs20." (PMID 28368013, 2017). "This emphasizes the additional benefits of TSLP-signalling blockade in conjunction with blockade of IL-7-signalling as a therapeutic strategy in rheumatoid arthritis and possibly other autoimmune diseases." (PMID 26110994, 2015). "While TSLP plays a pivotal role in allergic inflammation, the excess activity of this pro-inflammation cytokine implicates the initiation and progression of many different types of allergic, chronic inflammation and autoimmune diseases." (PMID 39726595, 2024). "TSLP was shown to promote Th17 differentiation and enhance arthritis in murine rheumatoid arthritis models, indicating the importance of TSLP in the differentiation of Th17 and the involvement of TSLP in the pathogenesis of autoimmune disease." (PMID 23194010, 2012). "These ex vivo studies demonstrated that the TAVO101 inhibited TSLP-driven allergic inflammation responses from its target cells which laid the foundation for its potential as a therapeutic treatment of TSLP-mediated allergic, chronic inflammatory and autoimmune diseases." (PMID 39726595, 2024). "Furthermore, as TSLP influences autoimmune diseases and certain skin conditions, SH-340 might hold promise in addressing these disorders." (PMID 37630370, 2023). "The role of TSLP in autoimmune diseases is largerly unknown, and only very few studies have started to explore the role of this pleiotropic cytokine in Th1- or Th17-driven autoimmune disorders." (PMID 30057581, 2018). "Both thymic stromal lymphopoietin (TSLP) and dendritic cells (DCs) are involved in many autoimmune diseases, but the potential roles of TSLP and DCs in bullous pemphigoid (BP) have not been clarified." (PMID 33029540, 2020).
autoimmune disease (continued). "As an increasing body of evidence suggested that MPs have potent proinflammatory activities and are potentially important mediators of inflammatory and autoimmune diseases, we have investigated in this study the role of MPs on BAFF, TSLP, and SLPI secretion by FLSs isolated from RA patients." (PMID 19291304, 2009).
chronic rhinosinusitis (18 papers, 2016 to 2026). Chronic form of sinusitis. "This study was performed to determine whether there was any association between abnormal DNA methylation of a thymic stromal lymphopoietin (TSLP) locus and pathogenesis of chronic rhinosinusitis (CRS)." (PMID 31768185, 2019).
inflammatory bowel disease (17 papers, 2014 to 2025). A spectrum of small and large bowel inflammatory diseases of unknown etiology. "TSLP has also been implicated in the regulation of intestinal immunity and inflammation in a mouse model of inflammatory bowel disease." (PMID 24573880, 2014). "Studies on Ac-AIP-1 in a TNBS colitis model show suppression of colon IL-10, TGF-β and TSLP and Treg cell accumulation, making the protein a novel therapeutic candidate for inflammatory bowel disease treatment." (PMID 36883013, 2023). "TSLP also acts on human and murine DCs by inhibiting IL-12 secretion which is a pro-inflammatory protein involved in Inflammatory Bowel Disease (IBD)." (PMID 26546058, 2015). "Considering the reported similarities between immunopathogenesis of ICB-induced colitis and inflammatory bowel disease (IBD), our findings on TSLP in the colon may provide an explanation for the observed link between the epithelium and IBD pathogenesis." (PMID 37427591, 2023). "Moreover, decreased TSLP production was found in mucosal biopsies from patients with inflammatory bowel disease (IBD)." (PMID 26919238, 2016). "The role of sf and lf TSLP in experimental inflammatory bowel disease is hampered by the absence of sf TSLP in the mouse." (PMID 30057581, 2018).
pulmonary fibrosis (15 papers, 2017 to 2025). Chronic progressive interstitial lung disorder characterized by the replacement of the lung tissue by connective tissue, leading to progressive dyspnea, respiratory failure, or right heart failure. "In this report, we describe and reflect on a newly discovered link between ST2 deficiency and TSLP-driven IL-9 elevation in the regulation of pulmonary fibrosis." (PMID 41465219, 2025). "Such blockade of TSLP strongly downregulated pulmonary levels of IL-9 and collagen indicative of attenuation of pulmonary fibrosis as well as upregulated terminal body weight indicative of alleviation of the overall disease severity." (PMID 41465219, 2025). "It was concluded that the antifibrotic effect of ST2 deficiency is hindered by the simultaneous activation of the TSLP–IL-9 axis in experimental bleomycin-induced pulmonary fibrosis." (PMID 41465219, 2025). "It has been well elucidated that IL‐25/IL‐33/TSLP plays an important role in allergic airway inflammation and remodeling, whereas their roles in idiopathic pulmonary fibrosis (IPF) still remained largely unclear." (PMID 36082495, 2022). "The important roles and mechanisms of IL‐25/IL‐33/TSLP are mainly elucidated by experimental murine lung fibrosis model induced by BLM or S. mansoni eggs." (PMID 36082495, 2022). "LIGHT can also regulate TSLP to promote the development of pulmonary fibrosis, which is a common complication of SMPP." (PMID 36618370, 2022). "Proteins‐H were biologically interesting: TNFRSF14 reported to control TSLP drives pulmonary fibrosis." (PMID 34962717, 2021). "The part of TSLP in MRC-5 cells indicated the potential therapeutic implication of TSLP in lung fibrosis of acute lung injury." (PMID 32413869, 2020). "Recently studies employing animal models proved that IL-25, IL-33, and TSLP have an emergent role in the generation of pulmonary fibrosis." (PMID 31581688, 2019). "Recently, TSLP has also emerged as an important cytokine in the pathogenesis of systemic sclerosis and idiopathic pulmonary fibrosis." (PMID 30013577, 2018). "It is also possible that the increased serum levels of TSLP and sIL-7Rα contributed to lung fibrosis." (PMID 30013577, 2018). "Despite the relations of the pulmonary fibrosis with IL-25, IL-33, and TSLP, the clinical implications of these cytokine remain poorly defined due to the small number of subjects (less than 15) examined in the previous studies." (PMID 28202030, 2017). "Seemingly contradictory, the genetic deletion of LIGHT attenuates bleomycin-induced pulmonary fibrosis in animal models through the abolition of Thymic stromal lymphopoietin (TSLP) expression." (PMID 28440314, 2017). "TSLP promotes lung fibrosis by directly acting on lung fibroblast." (PMID 36082495, 2022). "In addition to IL-33, TSLP has emerged as a candidate cytokine in the pathogenesis of pulmonary fibrosis by the elevated TSLP levels seen in both systemic sclerosis." (PMID 28202030, 2017). "Innate T helper type 2 (Th2) immune responses mediated by interleukin (IL)-33, thymic stromal lymphopoietin (TSLP), and IL-25 have been shown to play an important role in pulmonary fibrosis of animal models; however, their clinical implications remain poorly understood." (PMID 28202030, 2017). "Recently, it has been reported that TSLP expression increased in idiopathic pulmonary fibrosis, atopic dermatitis fibrosis and keloid scar tissue, and it has been reported that it induces transforming growth factor-β, and affects collagen synthesis and fibrocyte infiltration." (PMID 29140280, 2017). "Thus far, no studies about the relationship between cutaneous sarcoidosis and TSLP have been reported yet, although one study about idiopathic pulmonary fibrosis showed that TSLP level in the bronchoalveolar lavage fluid of pulmonary sarcoidosis was not higher than that of normal controls." (PMID 36046760, 2022).
pulmonary fibrosis (continued). "We have done a literature search using the following terms: (“idiopathic pulmonary fibrosis” OR “IPF” OR “lung fibrosis”) and (TSLP or “thymic stromal lymphopoietin” or IL‐25 OR IL‐17E OR IL‐33) from the database of PubMed published in English up to July 2018." (PMID 36082495, 2022). "IL‐25/IL‐33/TSLP and their corresponding receptors, that is, IL‐17BR/ST2L/TSLPR, are shown to be up‐regulated both in IPF patients and bleomycin (BLM)‐induced lung fibrosis mice model." (PMID 36082495, 2022). "For a more thorough characterization and verification of the 10-4ABFP cells, cytokines elevated during pulmonary fibrosis (TGF-β1, IL-33, IL-4, and TSLP) were screened to establish dose- and time-response curves." (PMID 33162897, 2020). "As far as we know, no previous studies reported that IL-25 and TSLP pathways leading to lung fibrosis might be impacted by pirfenidone." (PMID 31581688, 2019).
breast tumor (14 papers, 2012 to 2025). "Loss of baseline TSLP signaling in PyMttg TslprKO mice led to significantly earlier breast tumor onset (P = 0.0065) and increased tumor numbers per animal compared with PyMttg mice (P = 0.0353)." (PMID 35657353, 2022). "Using TSLP RNA in situ hybridization assays, we documented the loss of epithelial TSLP expression in the matched samples of primary breast tumors compared with their adjacent normal mammary glands." (PMID 35657353, 2022). "Pedroza‐Gonzalez and his colleagues demonstrated the association between TSLP and Th2 microenvironment in breast tumors." (PMID 31210014, 2019). "In particular, Emma L. Kuan and Steven F. Ziegler found that TSLP served as an essential growth and survival factor for breast tumor cells by inducing the expression of Bcl-2, an antiapoptotic protein." (PMID 38557942, 2024). "Recently, breast tumor-derived IL-1α was reported to act on tumor-infiltrating myeloid cells inducing the expression of thymic stromal lymphopoietin (TSLP), a factor that was crucial for tumor survival and metastatic spreading." (PMID 35743911, 2022). "The combination of anti-TNF-α and anti-IFN-γ blocking antibodies reversed the tumor-suppressing effect of TSLP induction and resulted in an accelerated breast tumor growth compared with IgG-treated group (p < 0.0001)." (PMID 36467403, 2022). "Recent studies have also shown that breast tumors produce the proinflammatory cytokine IL-1α, which then induces the production of thymic stromal lymphopoietin (TSLP) by tumor-infiltrating myeloid cells, especially neutrophils and monocytes." (PMID 31366131, 2019). "Breast tumor-derived IL-1α, acting on tumor-infiltrating myeloid cells, induced the expression of thymic stromal lymphopoietin (TSLP), which was not only a critical tumor survival factor, but is also required for the metastatic spread of the tumor cells." (PMID 31231372, 2019). "In addition, downregulation of TSLP signaling in breast tumor cells drastically reduced primary tumor growth and lung metastasis." (PMID 38557942, 2024). "Based on findings indicating TSLP production by PMNs in breast tumors, we decided to evaluate whether peripheral blood neutrophils could contribute as a source of TSLP in GBM tumors." (PMID 38557942, 2024). "Furthermore, we demonstrated that IL4-Rα expression on CD4+ T cells was required for the TSLP-induced suppression of PyMttg breast tumor growth." (PMID 35657353, 2022). "However, in WT mice, serum levels of TSLP correlated positively with malignant breast-tumor cells and melanoma growth, indicating the importance of TSLP in tumor progression." (PMID 30214685, 2018). "Additionally, another elegant study showed that human myeloid DCs expressing OX40L stimulate Th2 immunity in vitro, under the influence of thymic stromal lymphopoietin (TSLP) derived from breast tumor cells." (PMID 23762097, 2013). "By contrast, TSLP induction stimulates the specific expansion and antitumor functionality of CD4+ Th2 cells in spontaneous and cell line–derived breast tumors." (PMID 39782693, 2025). "Thus, TSLP may be an important factor of breast tumor progression and the prognosis of a patient." (PMID 25075970, 2014). "A study indicated that CAFs in GATA3+ breast tumours could produce TSLP+ DCs, which exist in tumour-draining lymph nodes but not in nondraining lymph nodes." (PMID 35936012, 2022).
colon cancer (14 papers, 2016 to 2025). "A recent study also found a significant decrease of TSLP in patients with colon cancer compared to tissues surrounding a tumor, as well as a negative association between TSLP levels and the score of clinical staging of colon cancer." (PMID 31210014, 2019). "The expression of TSLP mRNA in colon cancer tissue was increased compared to normal colon from the same patients." (PMID 40873585, 2025). "In contrast, TSLP is a cytokine known for its reported anti-tumor effects, directly promoting apoptosis in colon cancer cells." (PMID 39200479, 2024). "Using a xenograft mouse model of colon cancer, Yue and coauthors demonstrated that the peritumoral administration of TSLP reduces tumor growth by inducing the apoptosis of human colon cancer cells in a TSLPR-dependent manner." (PMID 36766801, 2023). "Our data are consistent with a previous study that evaluated the effects of TSLP on colon cancer and reported that high doses of TSLP induced apoptosis of colon cancer cells in vitro, and decreased tumor size after peritumor injection of TSLP." (PMID 36613920, 2022). "The study also reported that knocking down TSLPR (CRLF2) significantly reduced TSLP’s ability to induce colon-cancer-cell apoptosis." (PMID 36613920, 2022). "Together, our findings illustrate differences in the mechanism of action of TSLP in cutaneous melanoma and in colon cancer." (PMID 36107619, 2022). "The mRNA expressions of TSLP showed an increase of about 4-folds in colon cancer tissues compared to normal colon tissues (p < 0.001)." (PMID 34573368, 2021). "By analyzing the staining intensity, it was observed that protein levels of TSLP were significantly higher in colon cancer tissues than in normal colon tissues." (PMID 34573368, 2021). "We used four biopsies from colon cancer patients and applied a specific antibody, anti TSLP (Santa Cruz Biotechnology, Dallas, TX, USA; dilution 1/100)." (PMID 34573368, 2021). "We investigated 20 samples from colon cancer tissues and 20 samples from normal colon tissues from the same patient for TSLP expression." (PMID 34573368, 2021). "Yue and collaborators found decreased TSLP expression in human colon cancer and TSLP levels negatively correlated with the clinical staging score of cancer." (PMID 30057581, 2018). "Conversely, recent investigations in mouse models, and in early-breast and pancreatic human tumors, skin cancer and colon cancer, suggest a tumor-suppressing effect for TSLP." (PMID 30214685, 2018). "Our study revealed a novel anti-tumor role of TSLP by directly acting on human colon cancer cells through TSLPR signaling to induce their apoptosis." (PMID 26919238, 2016). "We performed western blotting to assess the phosphorylation levels of MARKs in TSLP-stimulated colon cancer cells." (PMID 26919238, 2016). "We here found significantly decreased TSLP levels in tumor tissues compared with tumor-surrounding tissues of patients with colon cancer and TSLP levels negatively correlated with the clinical staging score of colon cancer." (PMID 26919238, 2016). "Further investigation needs to explore the immunoregulatory effect of TSLP on colon cancer by using cancer model of immunocompetent mice and TSLP or TSLPR-deficient mice." (PMID 26919238, 2016). "Markedly increased protein levels of cleaved caspase-8 and caspase-9 were detected in TSLP-treated colon cancer cells, suggesting the involvement of both pathways." (PMID 26919238, 2016). "Taken together, these results demonstrate that TSLP is able to promote the apoptosis of colon cancer cells in a TSLPR-dependent manner." (PMID 26919238, 2016). "This was further confirmed by TSLP immunostaining of tumor sections from patients with stage A and stage D colon cancer showing that tumor tissues from stage A patients had much more TSLP-positive staining than those from stage D patients." (PMID 26919238, 2016).